SIRPG (signal regulatory protein gamma)
Description:
Probable immunoglobulin-like cell surface receptor. On binding with CD47, mediates cell-cell adhesion. Engagement on T-cells by CD47 on antigen-presenting cells results in enhanced antigen-specific T-cell proliferation and costimulates T-cell activation.
Synonyms: SIRP-b2; CD172g; SIRPB2; bA77C3.1; SIRPgamma
Tractability: Antibody: its Gene Ontology location is reachable by antibodies, with high confidence; UniProt predicts a signal peptide or a membrane-spanning region. PROTAC: ubiquitination databases record sites on it.
Gene: Protein-coding gene on chromosome 20 (1,629,152 to 1,657,779, reverse strand). Ensembl gene ENSG00000089012.
Subcellular location: Membrane
Pathways (Reactome):
Cell-Cell communication: Signal regulatory protein family interactions
Hemostasis: Cell surface interactions at the vascular wall
Gene Ontology:
Molecular function: protein binding
Biological process: positive regulation of cell population proliferation; positive regulation of cell-cell adhesion; positive regulation of T cell activation; cell-cell signaling; intracellular signal transduction; negative regulation of cell population proliferation; positive regulation of phagocytosis
Cellular component: membrane; plasma membrane
Genetic constraint (gnomAD): Loss-of-function variants: 33 observed, 32.39 expected, observed/expected ratio (o/e) 1.02, 90% interval 0.77 to 1.36. The upper end of that interval is the gene's LOEUF score, 1.36, which puts it in group 5 of 6, group 1 being the genes least tolerant of losing a copy. Missense variants: 494 observed, 475.16 expected, observed/expected ratio (o/e) 1.04, 90% interval 0.96 to 1.12. Synonymous variants: 207 observed, 185.77 expected, observed/expected ratio (o/e) 1.11, 90% interval 0.99 to 1.25.
Homologues: Orthologues: chimpanzee SIRPG (97% identical), macaque SIRPG (91% identical), dog SIRPA (64% identical), mouse Sirpb1a (54% identical), mouse Sirpb1b (54% identical), mouse Sirpb1c (54% identical), mouse Sirpa (53% identical), rat Sirpa (50% identical), mouse Gm5150 (26% identical), rat LOC100909964 (24% identical), mouse Sirpd (20% identical), rat AABR07008876.1 (18% identical). Paralogues in human: SIRPB1 (76% identical), SIRPA (73% identical), SIRPD (20% identical), SIRPB2 (19% identical).
Diseases named in the same sentence as SIRPG in open-access papers:
SIRPG is named in the same sentence as 34 diseases in open-access papers, as found by Europe PMC text mining. Sharing a sentence is not in itself a finding about the gene and the disease. The quoted sentences say what the papers report.
type 1 diabetes (9 papers, 2018 to 2025). "Several single nucleotide polymorphisms (SNPs) within the SIRPG locus are associated with increased susceptibility to type 1 diabetes (T1D) and narcolepsy." (PMID 41357240, 2025). "The V263A SNP was predicted to cause a conformational change altering the stability, structure, or function of SIRPG protein and was very likely a causal SNP of type 1 diabetes." (PMID 41357240, 2025). "Genomic studies have linked two specific genetic variations of SIRPG, rs2281808 (C > T; intronic) and rs6043409 (G > A; A263 V), to type 1 diabetes." (PMID 38274229, 2023). "The type 1 diabetes associated SNP near SIRPG was shown to modulate the risk of the disease by controlling the alternative splicing of the gene." (PMID 37224769, 2023). "Its function is still unclear but several SNPs at the SIRPG locus are associated with higher risk of type 1 diabetes." (PMID 34301319, 2021). "Signal regulatory protein gamma (SIRPγ) is a human T-cell specific protein with genetic variants associated with type 1 diabetes (T1D)." (PMID 32853219, 2020). "An interesting instance is SIRPG, a gene associated with type 1 diabetes, which we have previously found to act an expression quantitative loci (eQTL) in human total thymic tissue." (PMID 32393182, 2020). "Multiple GWAS studies have shown that the SNP rs2281808 TT variant, present within the SIRPG gene, is associated with autoimmune diseases, such as type 1 diabetes." (PMID 30337675, 2018). "Among these genes, five (IL6R, RBPJ, SKAP2, SIRPG, UBASH3A) harbour a nearby type 1 diabetes-associated SNP." (PMID 37224769, 2023). "Signal regulatory protein gamma (SIRPγ) is a human T-cell specific immunomodulatory protein encoded by the SIRPG gene with variants associated with autoimmunity in individuals with type 1 diabetes (T1D) in multiple GWAS studies." (PMID 32853219, 2020). "Finally, we found that the effects of some of these variants colocalized between NT1 and type 1 diabetes (CTSH G11R and SIRPG S286L, posterior probability = 1.0)." (PMID 37188663, 2023). "Here we report a novel association of reduced SIRPγ expression with two T-cell mediated autoimmune diseases including relapsing remitting multiple sclerosis (RRMS) and Type 1 diabetes (T1D)." (PMID 32853219, 2020).
autoimmune disease (5 papers, 2018 to 2024). A disorder resulting from loss of function or tissue destruction of an organ or multiple organs, arising from humoral or cellular immune responses of the individual to their own tissue constituents. "It was observed by Sinha and collaborators that the rs2281808 TT SNP in the SIRPG gene is associated with the expressive effector state of CD8+ T lymphocytes in autoimmune disease, despite the reduction in absolute count." (PMID 39066175, 2024). "Overall, our results show that the T allele of SNP rs2281808 in SIRPG is associated with two T-cell mediated autoimmune diseases, RRMS and T1D." (PMID 32853219, 2020). "We discovered that autoimmune disease risk SNP rs2281808 is associated with a reduction in SIRPγ expression on T-cells in humans." (PMID 30337675, 2018). "We also asked whether CD4 and CD8 T-cell SIRPγ expression levels in these autoimmune diseases was an exclusive function of the carrier associated intronic SNP or if there were other relevant disease-specific factors that contributed." (PMID 32853219, 2020). "Almost all variants identified (ZNF365, TNFSF4, NAB1, IKZF4-ERBB3, CTSC, DENND1B, SIRPG, and PRF1) are the same or strongly linked with markers associated with other autoimmune diseases." (PMID 37188663, 2023). "We have previously shown that reduced SIRPγ expression potentiates effector responses from human T-cells, suggesting that perturbed SIRPγ expression on T-cells may play a critical role in immune dysregulation of autoimmune diseases." (PMID 32853219, 2020). "Dysregulated SIRPG expression has also been demonstrated in other autoimmune conditions such as systemic lupus erythematosus (SLE), suggesting that SIRPγ may play a critical role in immune dysregulation in multiple different autoimmune diseases." (PMID 32853219, 2020).
Autoimmunity (4 papers, 2018 to 2024). The occurrence of an immune reaction against the organism's own cells or tissues. "The most substantial hint for the mechanistic role of SIRPG in autoimmunity comes from a recent study predicting that polymorphisms in SIRPG gene can interfere with transcription factors important in T-cell development." (PMID 30337675, 2018). "The most substantial hint for the mechanistic role of SIRPγ in autoimmunity comes from a recent study predicting that polymorphisms in SIRPG gene can interfere with transcription factors important in T-cell development." (PMID 30337675, 2018). "Despite the accumulating evidence connecting SIRPG with autoimmunity, there is a total knowledge gap about the role of SIRPγ in human T-cells and the functional significance of the TT variant." (PMID 30337675, 2018). "This suggests that reduced expression of SIRPγ may contribute to the heightened activity of T cells in autoimmune disorders." (PMID 39465721, 2024). "Future studies on the role of SIRPγ in immune regulation and dysregulation may enlighten our understanding of the targetable pathways involved in autoimmunity." (PMID 32853219, 2020). "Positive correlation between SIRPγlow T-cells and proinflammatory effector molecules from T-cells of RRMS and T1D patients suggest that reduced SIRPγ expression on T-cells could potentiate target organ-specific inflammation in autoimmunity." (PMID 32853219, 2020). "Additionally, we found that overall, SIRPγ expression on T-cells in patients with autoimmunity was significantly lower than healthy donors (HD), suggesting that SIRPγ expression may also be regulated by some as yet unknown disease-specific factors." (PMID 32853219, 2020). "However, SIRPγ’s potential mechanistic contribution to autoimmunity remains unclear due to a knowledge gap regarding its function in the immune system." (PMID 32853219, 2020). "Importantly, reduced SIRPγ-expression in RRMS and T1D subjects was not restricted to T variant, suggesting SIRPγ-expression is also regulated by disease specific factors in autoimmunity." (PMID 32853219, 2020).
lung carcinoma (4 papers, 2022 to 2024). "We found that high SIRPG expression in lung cancer cells mediates their cancer stem-like cell properties." (PMID 38833156, 2024). "It is important to note that although there have been studies on the role of SIRPG in regulating M1 macrophages in lung cancer, this field is still evolving, and further research is needed to fully understand the specific mechanisms involved." (PMID 38894865, 2024). "Expression characteristics of SIRPG in single cells were investigated using high-quality single-cell RNA sequencing (scRNA-seq) data from 27 lung cancer samples." (PMID 38833156, 2024). "Using scRNA-seq data from 27 lung cancer patients, we identified expression levels of SIRPG in different cell subtypes and found SIRPG was mainly expressed in T cells, especially CD8+ Tex and CD4+ Tregs." (PMID 38833156, 2024). "Collectively, our data with human lung cancer cell lines validate SIRPγ as a putative CSLC marker and indicate that this protein positively regulates key elements of the stem cell phenotypes, including tumorigenicity." (PMID 35229723, 2022). "We then performed qRT-PCR and Western blot assays using various commercial antibodies against SIRPγ to validate the expression of SIRPγ in lung cancer cells." (PMID 35229723, 2022). "SIRPG plays a crucial role in regulating the progression of lung cancer." (PMID 38894865, 2024). "Furthermore, SIRPG can also influence the development of lung cancer by regulating inflammation and immune cell infiltration." (PMID 38894865, 2024). "Recent studies found that SIRPG could become a potential biomarker for endometrial carcinoma and head and neck squamous cell carcinoma and might promote the immune escape of tumor cells in lung cancer." (PMID 38074669, 2023). "Our study identifies Hippo/YAP signaling as the first mechanism by which SIRPγ is engaged and reveals that targeting SIRPγ represents an immune- and CSLC-targeting strategy for lung cancer therapy." (PMID 35229723, 2022). "Thus, SIRPγ targeting represents a promising strategy for CSLC and lung cancer targeting." (PMID 35229723, 2022).
melanoma (4 papers, 2016 to 2024). A malignant, usually aggressive tumor composed of atypical, neoplastic melanocytes. "In NSCLC patients receiving PD-1 blockade, SIRPG is highly expressed in responders and patients with high levels of SIRPG expression were associated with better clinical outcomes, which was validated in the melanoma cohort." (PMID 38833156, 2024). "The current results suggest that high SIRPG expression was highly associated with an inflamed tumor immune microenvironment and favorable response to PD-1 blockade in NSCLC and melanoma." (PMID 38833156, 2024). "We previously reported that SIRPγ/CD47 blockade inhibits IFN-γ release in human tumor-antigen T-cell cross-priming assays using a CD8+ T-cell clone isolated and expanded from a melanoma patient." (PMID 34925315, 2021).
systemic lupus erythematosus (4 papers, 2018 to 2025). An autoimmune multi-organ disease typically associated with vasculopathy and autoantibody production. "Further, signal regulatory protein gamma (SIRPG) is connected with systemic lupus erythematosus (SLE), one of the maternal risk factors of IUGR." (PMID 30917529, 2019). "In line with this, the differential expression of SIRPG has also been reported in Systemic Lupus Erythematosus (SLE) patients." (PMID 30337675, 2018). "Further, Differential expression of SIRPG has also been reported in Systemic Lupus Erythematosus (SLE) patients, suggesting that SIRPγ might be pathologically relevant in multiple autoimmune diseases." (PMID 30337675, 2018). "Furthermore, elevated SIRPG transcript levels in PBMCs and/or protein levels in serum have been observed in patients with T1D, diabetic retinopathy, and active lupus (but not inactive lupus), suggesting SIRPG promotes immune responses and contributes to autoimmune pathogenesis." (PMID 41357240, 2025).
graft versus host disease (2 papers, 2021 to 2024). An immune system disorder that occurs after allogeneic hematopoietic stem cell transplant and is a reaction of donor immune cells against host tissues. "T cells with low levels of SIRPγ exhibit increased pathogenicity in vivo, as demonstrated in a graft-versus-host disease model." (PMID 39465721, 2024). "Since SIRPγ is absent in rodents, we took advantage of a graft-versus-host disease (GvHD) model, in which human PBMC injected in NSG-recipient mice would be chronically stimulated by the xenogeneic environment." (PMID 34925315, 2021).
lung adenocarcinoma (2 papers, 2022 to 2025). A carcinoma that arises from the lung and is characterized by the presence of malignant glandular epithelial cells. "SIRPG is upregulated in human lung adenocarcinoma, and its overexpression predicts poor survival outcomes." (PMID 39911848, 2025). "Here we showed that signal regulatory protein γ (SIRPγ) determined CSLC properties and immune evasiveness in a small population of lung adenocarcinoma (LUAD) cancer cells." (PMID 35229723, 2022).
Metastatic tumors (2 papers, 2020 to 2024). "Metastatic tumors from skin cutaneous melanoma (SKCM) showed significantly higher level of SIRPG expression than their primary tumor tissues, suggesting a hypothetically biological role of SIRPG in SKCM distant metastasis." (PMID 38833156, 2024).
relapsing-remitting multiple sclerosis (2 papers, 2018 to 2020). The most common clinical variant of multiple sclerosis, characterized by recurrent acute exacerbations of neurologic dysfunction followed by partial or complete recovery. "We show that T1D and relapsing remitting multiple sclerosis (RRMS) subjects have significantly greater frequency of rs2281808 T genetic variant, that correlates with reduced SIRPγ-expression in T-cells." (PMID 32853219, 2020).
diabetes (1 paper, 2024). "Interestingly, several studies suggested a potential link between elevated SIRPG and CTSH levels and diabetes susceptibility." (PMID 39408566, 2024).
glaucoma (1 paper, 2024). Increased pressure in the eyeball due to obstruction of the outflow of aqueous humor. "A total of 11 unique protein-coding genes posterior probability (PP) of H4 > 0.70 finally remained, including GSTM3 for senile cataract, WARS1, C3, IGFBP7, and PILRA for AMD, ECI1, LCT, and NPTXR for glaucoma, EFEMP1 for myopia, and SIRPG and SIGLEC14 for DR." (PMID 39408566, 2024).
Lewis lung carcinoma (1 paper, 2022). "Moreover, SIRPγ-overexpressing Lewis lung carcinoma cells were injected into C57BL/6 mice via the tail vein." (PMID 35229723, 2022).
liver cancer (1 paper, 2022). An epithelial or non-epithelial malignant neoplasm that arises from the liver. "Moreover, knockdown of SIRPγ in the liver cancer cell line LM3 also impaired cancer sphere formation, while its overexpression promoted it." (PMID 35229723, 2022).
lung adenoma (1 paper, 2022). A benign, well circumscribed epithelial neoplasm that arises from the bronchus or the lung parenchyma. "SIRPG knockin enhanced the lung adenoma growth in vivo induced by the KrasLSL-G12D/+ mutation." (PMID 35229723, 2022). "In KrasLSL-G12D/+SIRPGKI/+ compound mice treated with SIRPγ-blocking antibody, we found that targeting SIRPγ by LSB2.20 reduced the in vivo tumor growth of lung adenoma compared with the anti-IgG–treated group." (PMID 35229723, 2022). "To further address this concern, we generated a human SIRPG-knockin mouse model by CRISPR/Cas9-mediated homology-directed repair and studied the role of SIRPγ and its targeting in a KrasLSL-G12D/+ lung adenoma model with intact immunity." (PMID 35229723, 2022).
smallpox (1 paper, 2021). A condition that is caused by infection with Variola, and that is characterized by small, raised bumps. "Although smallpox was recently eradicated by vaccination, the virus was present for thousands of years; SIRPγ may have interacted with vCD47." (PMID 34925315, 2021).
uveal melanoma (1 paper, 2024). A melanoma derived from melanocytes of the uveal tract. "In SKCM, high SIRPG expression was associated with significantly longer OS whereas it was correlated with shorter OS in uveal melanoma." (PMID 38833156, 2024).